TCF21 (transcription factor 21)
Diseases named in the same sentence as TCF21 in open-access papers (continued):
Sharing a sentence is not in itself a finding about the gene and the disease.
myocardial infarction (5 papers, 2017 to 2025). Gross necrosis of the myocardium, as a result of interruption of the blood supply to the area, as in coronary thrombosis. "It has been shown that following myocardial infarction, myofibroblasts originate from Tcf21-positive cells." (PMID 39829679, 2025). "The majority of fibroblasts in the heart after acute myocardial infarction were derived from the Tcf21 lineage of tissue-resident fibroblasts." (PMID 38203553, 2023). "The deletion of YAP from transcription factor 21- (Tcf21) and Col1a1-expressing fibroblasts decreased their collagen deposition, proliferation, and activation after myocardial infarction." (PMID 34359886, 2021). "Furthermore, our findings that TCF21 and AHR are expressed in the atherosclerotic plaque and that they interact to modulate inflammatory genes and matrix modifying genes suggest that the interaction may directly promote plaque instability leading to myocardial infarction." (PMID 28481916, 2017).
adrenocortical carcinomas (4 papers, 2017 to 2021). "Our results suggest that enhancement of TCF21 expression levels may be a potential strategy to revert invasive abilities in adrenocortical carcinomas." (PMID 35201460, 2021). "Among these studies, a microarray analysis showed that 91 genes are differentially expressed between adrenocortical carcinomas (ACCs) and adrenocortical adenomas (ACAs) of adult patients, including the TCF21 gene, which was two times lower in ACCs than in ACAs or in normal adrenal cortex samples." (PMID 29520253, 2018). "In addition, using overexpression of Transcription Factor 21 in human adrenocortical carcinoma cells, we analyzed the protein expression of steroidogenic factor 1 using Western blotting." (PMID 28658440, 2017). "Additionally, Transcription Factor 21 overexpression inhibited the protein expression of steroidogenic factor 1 by 0.41-fold and 0.64-fold in two different adult adrenocortical carcinoma cell cultures, H295R and T36, respectively." (PMID 28658440, 2017). "Transcription Factor 21 is downregulated in adrenocortical carcinoma cells." (PMID 28658440, 2017).
lung adenocarcinoma (4 papers, 2009 to 2022). A carcinoma that arises from the lung and is characterized by the presence of malignant glandular epithelial cells. "In summary, we first used the GCBI bioinformatics analysis platform to identify DEGs that eliminated gender differences between lung adenocarcinoma and normal lung tissues, which showed that TCF21 is the hub gene." (PMID 28515486, 2017). "We finally found that decreased TCF21 mRNA expression is an unfavorable prognostic factor for patients with lung adenocarcinoma." (PMID 28515486, 2017). "Using comprehensive bioinformatics analyses, we reported that the decreased mRNA expression of TCF21 is an unfavorable prognostic factor for patients with lung adenocarcinoma." (PMID 28515486, 2017). "Then, using the comprehensive survival analysis platforms of Kaplan-Meier plotter and PrognoScan, we concluded that decreased mRNA expression of TCF21 is a poor prognostic factor in patients with lung adenocarcinoma." (PMID 28515486, 2017). "Consequently, we confirmed that TCF21 is the core gene in the DEGs between lung adenocarcinoma and normal lung tissues." (PMID 28515486, 2017). "Accordingly, we hypothesized that TCF21 expression may be a prognostic factor for patients with lung adenocarcinoma." (PMID 28515486, 2017). "Furthermore, using the comprehensive survival analysis platforms Kaplan-Meier plotter and PrognoScan, we showed that the decreased mRNA expression of TCF21 is an unfavorable prognostic factor for lung adenocarcinoma patients." (PMID 28515486, 2017). "Finally, we concluded that decreased mRNA expression of TCF21 is a predictor for poor prognosis in patients with lung adenocarcinoma." (PMID 28515486, 2017). "Furthermore, we used the comprehensive survival analysis platforms Kaplan-Meier plotter and PrognoScan to assess the prognostic value of TCF21 expression in lung adenocarcinoma patients." (PMID 28515486, 2017). "Furthermore, TCF21 is the core gene in the DEGs between lung adenocarcinoma and normal lung tissues." (PMID 28515486, 2017). "In fact frequent promoter hypermethylation of Tcf21 was reported in primary lung adenocarcinomas." (PMID 19812696, 2009). "Therefore, we hypothesized that TCF21 is the core gene in the DEGs between lung adenocarcinoma and normal lung tissues." (PMID 28515486, 2017). "Compared with non-neoplastic lung tissues, TCF21 was decreased in the lung adenocarcinoma samples." (PMID 28515486, 2017). "We consider that maybe TCF21 is a specific prognostic factor in lung adenocarcinoma rather than in lung squamous cell carcinoma, for which this point has not taken into account in previous studies." (PMID 28515486, 2017).
lung squamous cell carcinoma (4 papers, 2015 to 2025). "However, also using the comprehensive survival analysis platforms Kaplan-Meier plotter and PrognoScan, we found that TCF21 expression has no prognostic value in patients with lung squamous cell carcinoma (data not shown)." (PMID 28515486, 2017). "The low expression of TCF21 is an important factor for poor prognosis of LUAD, but not lung squamous cell carcinoma." (PMID 32686362, 2020).
cholangiocarcinoma (3 papers, 2020 to 2021). A carcinoma that arises from the intrahepatic biliary tree (intrahepatic cholangiocarcinoma) or from the junction, or adjacent to the junction, of the right and left hepatic ducts (hilar cholangiocarcinoma). "Existing research has elucidated that theinhibitory of transcription factor 21 mediated by PI3K-Akt signaling pathway could inhibit the progression of cholangiocarcinoma." (PMID 33478536, 2021).
fibrosis (3 papers, 2023 to 2025). the formation of excess fibrous connective tissue in an organ or tissue in a reparative or reactive process. "Deactivation of HSCs by Tcf21 (transcription factor 21), has been proved to suppress hepatic fibrosis progression in mice." (PMID 37008256, 2023). "Fibrosis-associated tdTomato was found only in PDGFRβ- and Tcf21-reporter mice, but not in NG2-and SMMHC-tdTomato mice." (PMID 39829679, 2025). "We observed upregulation of Tcf21 in DCM, suggesting its potential as a key regulatory factor in cardiac fibrosis in DCM." (PMID 38664790, 2024).
glomerular diseases (3 papers, 2020 to 2023). "Second, TCF21 was normally expressed in nuclei of podocytes and highly accumulate in both nuclei and cytoplasma of the injured podocytes in glomerular diseases, even was detected in urine." (PMID 36875100, 2023). "Then, the TCF21 expression in podocytes was semiquantitatively evaluated and compared to the magnitude of urinary protein or glomerular diseases." (PMID 32661376, 2020). "Focusing on its significance, we proved podocyte-expressed TCF21 in various glomerular diseases using kidney tissue from both humans and rat models." (PMID 32661376, 2020). "Herein we clarify the contributions of TCF21 to the regulation of proteinuria by detecting podocyte-expressed TCF21 in various glomerular diseases and evaluating its in- vitro effects." (PMID 32661376, 2020). "To elucidate its influence on glomerular disease, we have investigated TCF21 expression in human and rat kidney tissue, and its urinary concentration." (PMID 32661376, 2020). "To support this result, we also used Nephroseq datasets, and compared TCF21 mRNA expression among some glomerular diseases including healthy living donor, MGN and MCD." (PMID 32661376, 2020). "Next, we semi-quantitatively analyzed TCF21 expression using single immunohistochemistry and compared expression level among various glomerular diseases." (PMID 32661376, 2020). "It led us to suppose that the increase in urinary TCF21 in glomerular diseases resulted from some factors other than podocyte shedding." (PMID 32661376, 2020). "First, we histologically investigated the expression and localization of TCF21 in human normal glomeruli and various glomerular diseases using double immunohistochemistry." (PMID 32661376, 2020). "Based on this study, we demonstrated the transition in podocyte TCF21-expression of glomerular diseases and showed that it may function as a urinary biomarker in various kidney injuries." (PMID 32661376, 2020). "Many of the transcription factors have previously been shown to play a role in podocyte injury and glomerular disease, such as MAFB, TCF21, DACH1 and the recently reported FOXC1." (PMID 37681897, 2023).
hepatocellular carcinoma (3 papers, 2021 to 2025). A malignant tumor that arises from hepatocytes. "TCF21 DNA methylation levels were higher in hepatocellular carcinoma tissues than in adjacent non-tumor lung tissues." (PMID 40226362, 2025).
Obesity (3 papers, 2015 to 2025). Accumulation of substantial excess body fat. "Additionally, in Uygurs, visceral adipose tissue expression levels of TBX1 and TCF21 were greater in obesity group than in normal and T2DM groups and lower in T2DM group than in normal group (P < 0.01)." (PMID 26273678, 2015). "In addition, statistical analysis showed that the ratio of expression level of TBX1 to TCF21 (TBX1/TCF21) in obesity group was significantly greater than those in normal and T2DM groups (P < 0.01)." (PMID 26273678, 2015). "The TBX1 and TCF21 expression levels in the obesity group were significantly higher than those of normal and T2DM groups (P < 0.01); and the TBX1 and TCF21 expression levels in the T2DM group were significantly lower than those of normal and obesity groups (P < 0.01)." (PMID 26273678, 2015). "The ratio of expression level of TBX1 to TCF21 (TBX1/TCF21) in obesity group was significantly greater than those in normal and T2DM groups (P < 0.01), suggesting that the lipid metabolic activity of visceral adipose tissue in obesity individuals was lower than those in normal and T2DM individuals." (PMID 26273678, 2015).
osteosarcoma (3 papers, 2019 to 2023). A usually aggressive malignant bone-forming mesenchymal neoplasm, predominantly affecting adolescents and young adults. "rs12190287 (C > G) of TCF21 has been studied with Osteosarcoma risk in the Chinese population and was showing a higher risk of Osteosarcoma in the studied population." (PMID 32487238, 2020).
renal carcinoma (3 papers, 2018 to 2021). A carcinoma arising from the epithelium of the renal parenchyma or the renal pelvis. "However, no studies have functionally addressed the tumor suppressor activity of TCF21 in renal cancer cells." (PMID 29080283, 2018). "In renal cancer, the expression of KISS-1 was downregulated with TCF21 gene silencing." (PMID 35201460, 2021).
adenoma (2 papers, 2018 to 2021). A neoplasm arising from the epithelium. "We could be demonstrated a negative correlation between the level of TCF21 expression and methylation of its promoter in adenoma and carcinoma cells indicating the epigenetic control of TCF21 expression." (PMID 35201460, 2021). "Adult carcinomas express less TCF21 than adenomas, in addition, the KEGG pathway analysis has shown that BUB1B, among others genes, is negatively correlated with TCF21 expression." (PMID 29520253, 2018).
adrenal adenoma (2 papers, 2017 to 2021). "Transcription Factor 21 knockdown increased the mRNA expression of steroidogenic factor 1 by 5.97-fold in pediatric adrenal adenoma-T7 cells." (PMID 28658440, 2017). "We analyzed the gene expression of steroidogenic factor 1 using qPCR after silencing endogenous Transcription Factor 21 in pediatric adrenal adenoma-T7 cells through small interfering RNA." (PMID 28658440, 2017). "In addition, and also important, the downregulation of TCF21 in an adrenocortical adenoma cell culture, enable the migration and invasive ability of tumor adrenocortical cells when compared to control cells." (PMID 35201460, 2021).
breast tumor (2 papers, 2020 to 2021). "TCF21 is found mutated in several types of cancers Studies have shown a lower expression of TCF21 in breast tumor tissues corresponding to enhanced tumor size and increased lymph node metastasis." (PMID 32894086, 2020).
cardiac hypertrophy (2 papers, 2017 to 2021). "Together, these results demonstrate that loss of β-catenin in either Tcf21 or Postn lineage CFs leads to decreased cardiac hypertrophy after TAC-induced pressure-overload injury." (PMID 28959037, 2017). "Likewise, cardiac hypertrophy, as indicated by heart weight-to-body weight ratio, also was blunted with loss of β-catenin in either Tcf21 or Postn lineage cells." (PMID 28959037, 2017). "Xiang and colleagues showed that the conditional genetic loss of β-catenin in heart fibroblast (Transcription factor 21 (TCF21) + cells) and activated fibroblasts and myofibroblasts (Periostin+) lineages reduces fibrosis and ameliorates cardiac hypertrophy induced by pressure overload." (PMID 34210364, 2021).
Diabetes (2 papers, 2023 to 2024). "However, further studies are required to ascertain the role of TCF21 polymorphism in diabetes mellitus." (PMID 38250610, 2024). "In kidney tissue, the expression of DDX17 was also decreased in the Woroniecka Diabetes Glom database, which was in line with the DACH1 and TCF21 expression." (PMID 36875100, 2023).
diabetic kidney disease (2 papers, 2020 to 2023). Progressive kidney disorder caused by vascular damage to the glomerular capillaries, in patients with diabetes mellitus. "In fact, TCF21 protein levels were also elevated in the early stage of diabetic nephropathy in model mice." (PMID 36875100, 2023). "Even though diabetic nephropathy was not examined in our study, a previous gene-expression study using a mouse diabetic kidney disease (DKD) model highlighted significant changes in Tcf21 expression." (PMID 32661376, 2020).
focal segmental glomerulosclerosis (2 papers, 2023 to 2024). A renal disorder characterized by sclerotic lesions in the glomeruli. "Mice with podocyte-specific TCF21-knockout spontaneously developed proteinuria and exhibit FSGS (focal segmental glomerulosclerosis) lesions." (PMID 36875100, 2023).
Infertility (2 papers, 2021 to 2023). "Therefore, whether dysregulation of the TCF21+ population may be involved in the pathogenesis of testis fibrosis in certain contexts of infertility remains to be examined." (PMID 34162856, 2021).
Myocardial fibrosis (2 papers, 2019 to 2023). "Levels of myocardial fibrosis were assessed by Picrosirius red staining, which showed a significant reduction of fibrosis with fibroblast-specific deletion of Hsp47 compared with Tcf21-MCM controls after 4 weeks of TAC injury." (PMID 31393098, 2019). "To assess whether the attenuation of myocardial fibrosis and calcification progression by miR–129-5p may be explained by differences in expression of SOX9 and ASPN in CF, we employed lineage tracing of CF of the transcription factor 21 (Tcf21) lineage in mice (Tcf21MCM/+;R26EGFP mice)." (PMID 37154157, 2023).
prostate carcinoma (2 papers, 2016). A carcinoma that arises from epithelial cells of the prostate gland. "In prostate cancer, TCF21 interacts with AR and inhibits its transactivation through the recruitment of HDAC1." (PMID 27028856, 2016).
asthma (1 paper, 2024). "Interestingly, TCF21 and KLF3 loci have been previously identified as asthma risk-associated GWAS loci." (PMID 39107801, 2024).
colorectal tumors (1 paper, 2021). "The overexpression of TCF21 in two human colorectal tumor cells, HCT116 and HT29, increased KISS1 protein expression and reduced the expression of both metalloproteinases MMP2 and MMP9, which are involved in cell invasion." (PMID 33729392, 2021).
congenital heart disease (1 paper, 2020). "Recent evidence has confirmed the momentous role of TCF21 in epicardial cell differentiation, and it has been found that TCF21 rs12190287 polymorphism is associated with VSD, a congenital heart disease." (PMID 32582717, 2020).
diabetic cardiomyopathy (1 paper, 2024). Diabetic cardiomyopathy is a disorder of the heart muscle in people with diabetes. "Through exploration of the transcription factors, we identified Tcf21, Arnt, Stat5a, and Stat5b as potentially key players in the development of diabetic cardiomyopathy, particularly in regulating endothelial cells and myocardial cells." (PMID 38664790, 2024).
esophageal cancer (1 paper, 2020). A primary or metastatic malignant neoplasm involving the esophagus. "Out of 12 SNPs, two SNPs rs12190287 of TCF21 and rs10046 of CYP19A1 were significantly associated with esophageal cancer with Odds Ratio (OR) 1.412 (1.09–1.8 at 95% CI, p = 0.008) and 1.54 (1.21–2.072 at 95% CI, p = 0.0007) within the population of Jammu and Kashmir." (PMID 32487238, 2020).
Glomerular sclerosis (1 paper, 2023). Accumulation of scar tissue within the glomerulus. "Mechanically, we speculated that the low expression of DDX17 might further down-regulate the activity of TCF21 and DACH1, worsen the glomerular sclerosis and renal interstitial fibrosis." (PMID 36875100, 2023).
hydronephrosis (1 paper, 2012). Collection of urine in the renal pelvis that results in dilatation of the renal pelvis and calyces. "Mice with deletion of β-catenin from Tcf21-expressing cells are born with hypoplastic kidneys, hydroureters and hydronephrosis." (PMID 22792366, 2012).
infiltrative ductal carcinoma (1 paper, 2016). "Intriguingly, stratified analyses based on pathological type indicated that TCF21 rs12190287 polymorphism was only associated with the reduced risk of infiltrative ductal carcinoma under all comparison models." (PMID 27270650, 2016). "Stratified analyses based on pathological type indicated that TCF21 rs12190287 polymorphism was only associated with the reduced risk of infiltrative ductal carcinoma." (PMID 27270650, 2016).
inflammatory bowel disease (1 paper, 2015). A spectrum of small and large bowel inflammatory diseases of unknown etiology. "Interestingly, enrichment for TCF21 target genes was also found among other genome wide association phenotypes, including height and inflammatory bowel disease, suggesting a functional profile important for basic cellular processes in non-vascular tissues." (PMID 26020271, 2015). "We also found that the candidate sets of GWAS genes associated with the CAD related trait platelet number and a disease phenotype related to a dysfunctional immune system, inflammatory bowel disease (IBD), also showed a high degree of enrichment for TCF21 target genes among the GWAS gene sets." (PMID 26020271, 2015).
kidney injuries (1 paper, 2020). "Also, we sought to establish the hypothesis that urinary TCF21 would be a useful biomarker related with kidney injuries." (PMID 32661376, 2020).